FCF1 (FCF1 rRNA-processing protein)
Description:
Part of the small subunit (SSU) processome, first precursor of the small eukaryotic ribosomal subunit. During the assembly of the SSU processome in the nucleolus, many ribosome biogenesis factors, an RNA chaperone and ribosomal proteins associate with the nascent pre-rRNA and work in concert to generate RNA folding, modifications, rearrangements and cleavage as well as targeted degradation of pre-ribosomal RNA by the RNA exosome.
Synonyms: C14orf111; CGI-35; Bka; UTP24
Tractability: Small molecule: a structure with a bound ligand is known. PROTAC: ubiquitination databases record sites on it; its protein half-life has been measured.
Gene: Protein-coding gene on chromosome 14 (74,713,144 to 74,738,620, forward strand). Ensembl gene ENSG00000119616.
Subcellular location: Nucleus, nucleolus
Subcellular location (Human Protein Atlas): Nucleoplasm
Pathways (Reactome):
Metabolism of RNA: Major pathway of rRNA processing in the nucleolus and cytosol; rRNA modification in the nucleus and cytosol
Gene Ontology:
Molecular function: protein binding; RNA binding
Biological process: ribosomal small subunit biogenesis; maturation of SSU-rRNA
Cellular component: small-subunit processome; nucleolus; nucleoplasm
Genetic constraint (gnomAD): Loss-of-function variants: 9 observed, 15.46 expected, observed/expected ratio (o/e) 0.58, 90% interval 0.35 to 1.02. The upper end of that interval is the gene's LOEUF score, 1.02, which puts it in group 4 of 6, group 1 being the genes least tolerant of losing a copy. Missense variants: 95 observed, 113.56 expected, observed/expected ratio (o/e) 0.84, 90% interval 0.71 to 0.99. Synonymous variants: 46 observed, 40.43 expected, observed/expected ratio (o/e) 1.14, 90% interval 0.9 to 1.46.
Homologues: Orthologues: chimpanzee FCF1 (100% identical), macaque FCF1 (100% identical), dog FCF1 (99% identical), pig FCF1 (99% identical), guinea pig Fcf1 (99% identical), mouse Fcf1 (98% identical), rat Fcf1 (98% identical), tropical clawed frog fcf1 (89% identical), zebrafish fcf1 (88% identical), Drosophila melanogaster Bka (68% identical), Caenorhabditis elegans F30A10.9 (60% identical). Paralogues in human: UTP23 (24% identical).
Diseases named in the same sentence as FCF1 in open-access papers:
FCF1 is named in the same sentence as 5 diseases in open-access papers, as found by Europe PMC text mining. Sharing a sentence is not in itself a finding about the gene and the disease. The quoted sentences say what the papers report.
breast carcinoma (2 papers, 2022). "FCF1 is a potential marker of circulating breast cancer cells for detecting metastasis." (PMID 36313471, 2022). "As a result of our algorithm, we identified a signature of 5 CTC-specific genes, i.e., ADPRHL1, ELF3, FCF1, TFF1 and TFF3, and explored its clinical significance according to their expression in CTC-enriched blood samples in our breast cancer case series." (PMID 35216615, 2022).
astrocytoma (1 paper, 2017). "No fusions involving LYNX1 have been reported in the literature so far, but the suggested fusion partner FCF1 was involved in a TIMM9-FCF1 fusion in an astrocytoma." (PMID 28893231, 2017).
tumor (2 papers, 2022 to 2024). "Significant differences were observed between tumor and normal samples for MRI1| chr19:13883962, GBP4| chr1:89649327, and FCF1| chr14:75203040." (PMID 39091293, 2024).
FCF1 also shares sentences with these, for which no sentence is quoted: cancer (1 paper); heart failure (1).